MTOR (mechanistic target of rapamycin kinase)
Diseases named in the same sentence as MTOR in open-access papers (continued):
Sharing a sentence is not in itself a finding about the gene and the disease.
cancer (continued). "Similarly, the Akt/mTOR pathway is a crucial signaling network involved in regulating cell growth and survival, and its dysregulation is linked to the growth and development of cancer." (PMID 37571343, 2023). "Therefore, progress in defining the molecular mechanisms underlying mTORC2 function in cancer could pinpoint more selective strategies for targeting the mTOR pathway." (PMID 37877351, 2023). "Finally, we investigated whether the suppression of autophagic induction was involved in the antigrowth effects of metformin in DPP-4-deficient cancer cells, similar to the effect of the mTOR inhibitor rapamycin." (PMID 37760498, 2023). "Deregulation of the PI3K-Akt-mTOR pathway may cause cancer recurrence and metastasis." (PMID 35586809, 2022). "In this signaling pathway, the mammalian target of rapamycin (mTOR) protein-kinase is a master regulator that acts through two complexes: mTORC1 and mTORC2, playing pivotal roles in the induction of tumor growth, where aberrant activation of their components is associated with many cancer types." (PMID 35359411, 2022). "Because cancer cells could develop resistance to inhibitors of protein translation and this class of drugs may not directly cause tumor cell death, identifying other regimens which synergize with mTOR inhibitors is warranted." (PMID 36043466, 2022). "Because the mTOR signaling plays pivotal roles in diverse cellular processes, it is not surprising that dysregulation of this fundamental pathway has been associated with the pathogenesis of a broad range of human diseases (e.g., cancers, metabolic, and neurodevelopmental disorders)." (PMID 35013125, 2022). "Therefore, the mTOR pathway and its downstream cellular process of autophagy might be implicated in the regulation of cancer stemness in EC and may open doors to novel targeted therapies." (PMID 35406578, 2022). "In addition, mTOR inhibitors have replaced cycloserine and tacrolimus because of their recently reported anti-tumor effects because of which they have a lower risk for cancer than that associated with previous immunosuppressant agents." (PMID 34419041, 2021). "In addition, the mTOR activation has been associated with increased drug resistance in cancers." (PMID 34540820, 2021). "The BEZ235-treated cells showed a significant inhibition of the PI3K/AKT/mTOR signaling molecules and an increase in p-STAT3Tyr705 levels, indicating that re-activation of the PI3K/AKT/mTOR pathway in PTEN-deficient cancer cells may involve inhibition of STAT3 activity." (PMID 33431808, 2021). "Additionally, amplification and mutations of mTOR kinase and Rictor could also influence mTOR deregulation in cancers." (PMID 35029792, 2021). "Studies have shown that Deregulation of the mammalian TOR (mTOR) signaling network is associated with cancer, because MTOR is activated in a variety of cellular processes, such as tumorigenesis, angiogenesis, and lymphocyte activation, and is dysregulated in a variety of cancers." (PMID 33948902, 2021). "Moreover, CVBD causes cancer cell death of autophagy associated with the AKT/mTOR pathway." (PMID 33816313, 2021). "Thus, the inhibition of LAT1 and ASCT2 expression levels could represent a promising therapeutic approach for CRC since it would reduce the AA intake, consequently causing mTOR pathway inhibition and compromising cancer cell proliferation." (PMID 33669301, 2021).
cancer (continued). "However, the second-generation mTOR inhibitors caused several feedback loops that may trigger cancer cell survival and metastasis." (PMID 32887218, 2020). "Extensive research during the last decades has attributed a crucial role for mTOR in the regulation of fundamental cellular processes as protein synthesis, autophagy, and oxidative stress and demonstrated that deregulated mTOR signaling is implicated in cancer progression and aging." (PMID 32111081, 2020). "Thus, these modifications in the suppression of mTOR associated with elevated autophagy further support the concept that autophagy may also be exacerbated in patients with cancer cachexia." (PMID 32230855, 2020). "However, equally, mTOR inhibitors are thought to have anti-proliferative effects which may reduce the risk of cancer." (PMID 32605413, 2020). "The authors of this study showed that the CIS-deficient NK cells had improved metabolic fitness, caused by upregulated mTOR activity, suggesting that the mTOR inhibitors that are currently being trialed for various cancers may inadvertently dampen NK cell metabolic activity and therefore function." (PMID 33120910, 2020). "Interestingly, cell senescence in COPD has been linked to mTOR activation as well as in cancer." (PMID 32196072, 2020). "In addition, MEN1 could act as a tumor suppressor gene by regulating the mTOR signaling pathway (a pathway that has been implicated in cancer progression) to restore CD8+ T cell activity and function." (PMID 31349612, 2019). "Since viral vectors rely on host cell metabolism, we speculate that starvation-induced modification of the nutrient-sensing PI3K/Akt/mTOR pathway may also alter the cellular environment in HT-29 cells, and may potentially render cancer cells more susceptible to MeV infection." (PMID 31284426, 2019). "Indeed, mTOR mutations have been identified in human cancers." (PMID 31817676, 2019). "In addition, mTOR is associated with cell metabolism and cancer cell growth." (PMID 30420728, 2018). "For example, senescent beta cells overproduce insulin and thus activate mTOR in hepatocytes, adipocytes and other cells, causing their hyperfunction, which in turn leads to metabolic syndrome (obesity, hypertension, hyperlipidemia and hyperglycemia) and is also a risk factor for cancer." (PMID 30594910, 2018). "Interestingly, an association between miR-99b and mTOR has also been observed in cancer cells." (PMID 30544973, 2018). "Moreover, the promotion of autophagy linked to mTOR inhibition may mediate some effects of mTOR on cancer." (PMID 30393233, 2018). "mTOR folate sensing may have broad biological significance because of the critical role of folate in normal cell function and the wide range of disorders, including cancer, that have been linked to folate availability." (PMID 28638048, 2017). "Taken together, our study indicated that ~72% (n = 71/98) of NPC samples harbored mutations in one of the four cancer pathways (EGFR-PI3K-Akt-mTOR, NOTCH, NF-κB, DNA repair) which may be potentially useful as predictive biomarkers of response to matched targeted therapies." (PMID 28256603, 2017). "Indeed, high expression of p4E-BP1 has been associated with mTOR-pathway activation and cancer." (PMID 29137436, 2017). "Therefore, it is possible that the effect of this polymorphism on MTOR expression may be cancer type-specific." (PMID 28280736, 2017). "Therefore, copy loss is a recurrent feature in cancers associated with mTOR activation." (PMID 28640831, 2017). "In addition, several other limitations of targeting mTORC1 in cancer therapy have been described, including treatment resistant mutations of mTOR, activation of alternate proliferative signaling pathways, and intratumoral heterogeneity of mTOR activity." (PMID 28280521, 2017).
cancer (continued). "In addition, mTOR phosphorylation at the serine 2448 site improves the efficiency of mRNA translation, increases the expression of a series of cell proliferation and differentiation associated proteins, and promotes cancer cell development and progression." (PMID 29234489, 2017). "However, because Han Chinese is the largest ethnic group in the world and as the gene pool reflects a long history of immigrations and intermarriages with other ethnic groups, these data represent the complexity of the impact of mTOR polymorphisms on cancer development." (PMID 27462867, 2016). "Besides, the mechanisms underlying mTOR protein degradation in normal and cancer breast cells are still largely unknown." (PMID 27748082, 2016). "Moreover, activating-mutations within mTOR itself exist in multiple cancer types and may predict therapeutic response to mTOR-targeted therapy." (PMID 27015560, 2016). "In addition to mediating rapamycin’s clinical use for preventing graft rejection after organ transplantation and for treating autoimmune disorders, the components of the mTOR pathway have also been implicated in many other conditions including obesity related type 2 diabetes and cancer." (PMID 26433385, 2016). "Mammalian target of rapamycin (mTOR) gene polymorphisms exert the major effects on the regulation of transcriptional activity and miRNA binding or splicing, which may be associated with cancer risk by affecting mTOR gene expression." (PMID 27533457, 2016). "Thus, mTOR signalling may represent a nodal point linking pro-senescence and pro-tumourigenic cellular pathways; inhibition of mTOR activity may in part prevent cancer associated with age-related deregulation of cell signalling." (PMID 25388238, 2015). "Interestingly, recent studies show that the mammalian target of rapamycin (mTOR) kinase and downstream effectors may be implicated in the development of chronic inflammatory, neuropathic, and cancer pain." (PMID 25685786, 2015). "Furthermore, mutation of mTOR itself contributes to the risk of various cancers." (PMID 25906254, 2015). "Moreover, the pharmacological modulation of this MAM-localized complex could be used as a novel therapeutic intervention to modulate cell fate in cancers with AKT/MTOR mutations." (PMID 26284195, 2015). "Altered protein glycosylation translated by the expression of the sialyl-Tn antigen (STn) and its precursor Tn as well as the activation of the PI3K/Akt/mTOR pathway are cancer-associated events that may hold potential for patient stratification and guided therapy." (PMID 26569621, 2015). "In light of the critical role of mTOR in maintaining proper cellular functions, it is biologically plausible that genetic variations in this gene may affect cancer risk and clinical outcome of cancer patients." (PMID 24816861, 2014). "Abnormally increased expression of mTOR was associated with carcinogenesis, and its functional single nucleotide polymorphisms (SNPs) may regulate the expression of mTOR and thus contribute to cancer risk." (PMID 23940798, 2013). "Furthermore, growing evidence links miRNA deregulation of mTOR pathways to carcinogenesis in several human neoplasms, and their molecular signatures of deregulation have been associated with clinical features of several cancers." (PMID 23434669, 2013).
cancer (continued). "And there have been few studies to date addressing the role of common, functional variants in the mTOR gene as PCa susceptibility factors, together with some variations of other pivotal genes in this pathway have been investigated as weak or null associations with cancer risk." (PMID 23940798, 2013). "Thus, the mTOR pathway is functionally linked to the self-renewal of cancer stem-like cells." (PMID 24231729, 2013). "The identification of novel proteins that are involved in MAPK or AKT/mTOR signaling and differentially expressed between normal and cancer cells will provide mechanistically distinct therapeutic targets with the potential to inhibit these key cancer-associated pathways." (PMID 23676467, 2013). "Moreover, increased AKT/mTOR activity has also been associated with decreased apoptosis in cancers." (PMID 23285024, 2012). "Thus, coordinate mTOR and autophagy inhibition leads to an imbalance between ROS production and defense, causing necroptosis that may enhance cancer treatment efficacy." (PMID 22848625, 2012). "While a comprehensive review of mTOR’s role in disease processes is beyond the scope of this report, it is important to understand the mTOR signaling mechanism as it underlies many disease processes and has served to guide cancer therapeutic development and treatment." (PMID 23369283, 2012). "Notably, mutations causing hyper-activation of mTOR are common in cancers." (PMID 22574221, 2012). "However, aberrant activation of this pathway, such as those associated with mammalian target of rapamycin (mTOR), is observed in various cancers, leading to uncontrolled protein synthesis and the subsequent transformation of normal cells to more aggressive cancerous cells." (PMID 23029619, 2012). "The PI3K/AKT/mTOR pathway may also be involved in mediating the response to cancer treatment; one study has claimed associations between SNPs in several pathway genes and several esophageal cancer outcomes including recurrence risk, survival and treatment response." (PMID 21949775, 2011). "Thus, levels of phosphorylated 4E-BP1 may reflect contributions of mTORC1-signalling to cancer-associated translational deregulation, and consequently the sensitivity of such deregulated cells to mTOR inhibition." (PMID 21320304, 2011). "Indeed, mTOR regulates cell growth, proliferation and survival and is at the crossroads of different signaling pathways that are frequently mutated in various types of cancer." (PMID 24212820, 2011). "Thus, overactivation of mTOR due to dysregulation of upstream pathways, leading to abnormal activities in cell progression, angiogenesis, cell metabolism and apoptosis has been implicated in various cancer types." (PMID 21584218, 2010). "The AKT pathway, frequently stimulated in cancer and chronic inflammation, enhances cell survival and suppresses autophagy via mTOR activation." (PMID 41516397, 2026). "Aberrant activation of the phosphoinositide 3-kinase/alpha-serine/protein kinase B/mammalian target of rapamycin (PI3K/AKT/mTOR) pathway plays a key role in cancer development, making it an attractive therapeutic target." (PMID 41677168, 2026). "Genetic or epigenetic changes that lead to abnormal development of signalling through cellular pathways such as MAPK, PI3K/AKT/mTOR, Wnt/β-catenin play an important role in driving cancer." (PMID 42256398, 2026). "This review examines various cancer types, their associated risk factors, and critical molecular pathways, with the PI3K/Akt/mTOR and Wnt/β-catenin pathways, that facilitate cancer progression." (PMID 41869441, 2026).
cancer (continued). "The contribution of signalling pathways (PI3K/AKT/mTOR, MAPK, Notch, Wnt/β-catenin, and Hedgehog) to hypoxia, cancer-associated fibroblasts (CAFs), and tumour-associated macrophages (TAMs) in sustaining CSC niches will be discussed." (PMID 41751352, 2026). "This review delineates how cancer cells subvert branched-chain amino acid metabolism to fuel anabolic processes, activate oncogenic signaling cascades including mTOR and PI3K/AKT, and remodel the tumor microenvironment." (PMID 41769003, 2026). "The PI3K/Akt/mTOR and other cancer-related pathways were identified to be engaged in functional enrichment." (PMID 42206177, 2026). "The pathway is often disrupted in cancer cells, making mTOR an attractive target for cancer treatment." (PMID 41427517, 2026). "Mechanistic studies confirmed that PEC effectively suppressed the AKT/mTOR signaling pathway, a critical regulator of both autophagy and apoptosis in cancer cells." (PMID 41924135, 2026). "The mTOR pathway is a central driver of aging-related diseases, such as cancer, chronic inflammation and neurodegeneration; pharmacological inhibition with rapamycin is associated with reduced aged-related morbidity and increased lifespan across species." (PMID 42207784, 2026). "The PIK3/AKT/mTOR signaling pathway, a classic cell signaling cascade, is among the most commonly activated pathways in malignant tumors, including EC." (PMID 41602366, 2026). "Here, we demonstrate that the palmitoylation enzyme Zinc Finger DHHC-Type Containing 9 (ZDHHC9) activates the mTOR signaling pathway, thereby accelerating cancer progression and highlighting its potential role in RCC." (PMID 41856969, 2026). "The mTOR signaling cascade plays a central role in tumor progression by regulating key processes such as cancer cell survival, apoptosis, autophagy, and angiogenesis." (PMID 41362734, 2026). "The AKT/mTOR signaling pathway plays a key role in the development of multiple cancers by regulating cell growth, proliferation, metabolism and apoptosis." (PMID 41513632, 2026). "This review discusses the potential application of 37 mTOR pathway-modulating compounds, many originally developed for cancer treatment, given their shared molecular targets." (PMID 42267529, 2026). "Cancer cells under oxidative stress, hypoxia, and nutritional deficiency activate AMPK signaling, which inhibits the mTOR, thereby promoting autophagy." (PMID 41346764, 2026). "The PI3K/AKT/mTOR pathway is frequently dysregulated in cancer, contributing to tumor progression, drug resistance, and poor prognosis." (PMID 41726721, 2026). "The interplay between cytotoxic cytokines (granzymes A and B), immune cells like CTLs and NK cells, and survival pathways such as PI3K/AKT/mTOR and NF-κB underscores the complexity of the immune response and cancer biology." (PMID 40006976, 2025). "Central to cellular metabolism regulation is the mTOR pathway, which acts aberrantly in cancer cells and has multiple effects on cellular metabolism." (PMID 40149420, 2025). "In cancer cachexia, mTOR signaling is frequently downregulated, leading to impaired muscle protein synthesis and enhanced autophagic activity, both of which contribute significantly to progressive muscle wasting." (PMID 41476922, 2025). "NVPBEZ235, a dual inhibitor of PI3K and mTOR, has shown promise in inhibiting the growth of various cancers." (PMID 40771929, 2025). "At concentrations of 0.5–5 μM in NDM, CVM-A effectively inhibited cell survival by suppressing phosphorylation of Akt and mTOR—key mediators of cancer cell adaptation to metabolic stress." (PMID 40648084, 2025). "mTOR signaling enhances mitochondrial biogenesis and energy production, supporting cancer cell growth and survival." (PMID 40382494, 2025). "The mechanistic or mammalian target of rapamycin (mTOR) signaling pathway is involved in cancer cell proliferation and survival and is usually active in mRCC." (PMID 40661855, 2025).